CD24 (CD24 molecule)
Diseases named in the same sentence as CD24 in open-access papers (continued):
Sharing a sentence is not in itself a finding about the gene and the disease.
breast cancer (continued). "For example, it is unnecessary to call “CD44(+)/CD24(-) and ALDH1(+)” breast cancer cells as CSC 843-846, since “CD44(+)/CD24(-) and ALDH1(+)” defines them more specifically and clearly than the equivocal “CSC”." (PMID 32226506, 2020). "Then, another study indicates that CD24 and CD44 are cancer stem cells which can promote the development of breast cancer." (PMID 32558224, 2020). "Breast cancer was the first solid tumor where CSC was identified, and the markers used to identify them in this disease are CD24/CD44 and aldehyde dehydrogenase (ALDH)." (PMID 31924241, 2020). "A recent study reported that breast cancer stem cells were inhibited by benztropine mesylate in vitro by using stem cell markers such as aldehyde dehydrogenase activity, CD44+/CD24- phenotype, and the number of spheroids." (PMID 32102440, 2020). "Inhibition of ATM increased radiation sensitivity of the isolated CD44+/CD24- cell, which suggests that ATM is a potential target to improve radiation sensitivity in breast cancer therapy." (PMID 33680952, 2020). "CD44+/CD24-/low CSCs, derived from breast cancer, exhibit migration potential that increases with tumor grade, while a human CD44+ CD24-/low Lin- and mouse Thy1+ CD24+ Lin- CSC-enriched population exhibits low ROS levels and high expression of anti-ROS genes." (PMID 32658903, 2020). "Breast cancer stem cells (BCSC) have a number of markers, such as CD44, CD24, aldehyde dehydrogenase 1 (ALDH1), among others." (PMID 33102470, 2020). "CD24 regulates the activity of the chemokine receptor CXCR4 by affecting its localization in the plasma membrane lipid rafts of pre‐B cells and breast carcinoma cells." (PMID 32394616, 2020). "The results of our previous experiment with clove buds showed a significant decrease in CD24 and CD44 expression, and on the other hand, an increase in ALDH1A1 expression in treated mammary carcinomas." (PMID 32204409, 2020). "High expression of CD44 and low expression of CD24 (CD44+/CD24−) are useful for identifying and isolating the cells with stem-like properties in normal mammary tissues and breast carcinomas." (PMID 33217982, 2020). "The sorted and unsorted fractions of breast cancer cells via CD44, CD24, ALDH, mammospheres, and adherent cell cultures of breast cancer cell lines were analyzed for DNA profiling by array CGH and methylation profiling." (PMID 31013960, 2019). "In this study we evaluated for the first time the prognostic significance of TWIST1, CD24, CD44, and ALDH1 transcript quantification in EpCAM-positive circulating tumor cells isolated from peripheral blood of early stage breast cancer patients." (PMID 31261917, 2019). "Pyrvinium pamoate, an anthelmintic drug and inhibitor of the Wnt/β-catenin pathway, prevented the proliferation of breast cancer cells, especially CD44+CD24−/low and ALDH+ CSCs, via downregulating NANOG, OCT4, and SOX2." (PMID 31137841, 2019). "In breast cancer cell lines, PARP inhibitor (Olaparib) can significantly decrease the proportion of BCSCs with CD44+/CD24−/low/ESA+ cell surface marker, indicating the potential activity of PARP inhibitor in anticancer stem cells." (PMID 31555586, 2019). "In conclusion, detection of TWIST1 overexpression and stem-cell (CD24, CD44, ALDH1) transcripts in the EpCAM+ CTC fraction provides prognostic information in early stage breast cancer patients." (PMID 31261917, 2019). "In this study, it was also found that the CD44+ and CD24- phenotype is equally distributed among ALDH-positive and ALDH-negative MDA-MB-468 breast cancer cells." (PMID 30845764, 2019). "We found that miR‐200c was weakly expressed in both breast cancer cells and CD44+CD24− phenotype stem cells." (PMID 31599500, 2019). "High levels of YAP/TAZ expression are associated with reductions in metastasis-free survival in patients with breast cancer and adverse features of the disease; TAZ is essential for sustaining the self-renewal of CD44+CD24−/low BCSCs." (PMID 31336602, 2019).
breast cancer (continued). "We found that miR‐200c was down‐regulated in both breast cancer cell lines and CD44+CD24− phenotype breast cancer cell line stem cells." (PMID 31599500, 2019). "The aim of the current study was to evaluate the prognostic significance of TWIST1, CD24, CD44, and ALDH1 mRNA quantification in EpCAM-positive circulating tumor cells from early stage breast cancer patients with a long follow-up." (PMID 31261917, 2019). "In an analysis of 466 invasive breast carcinomas and eight breast cancer cell lines, basal-like breast cancer harbored the highest percentage of tumor cells with the CSC phenotype CD44+CD24−/low and ALDH1 positivity." (PMID 31505803, 2019). "Assessment of the expression of other BCSC markers -ALDH1A1, EpCAM, CXCR4, and CD133 in stable NRF1 overexpressing CD44+CD24− and CD44+CD24+ subpopulations showed as many as 10 different downstream breast cancer progenitor cell subpopulations." (PMID 30486409, 2018). "Their identification from tumor samples and mammary cancer cell lines has been based mainly on CD44, CD24, and ALDH1 phenotypes." (PMID 30092754, 2018). "Although CD44 and CD24 expression is a poor prognostic marker for different tumours including breast cancer, the role of CD44 and CD24 in paclitaxel resistance of breast cancer cells stimulated by E2 needs further study." (PMID 30179299, 2018). "For instance, ALDH+ bCSCs are more common of luminal and HER2 subtypes, and CD24−/CD44+ are enriched in basal-like and Claudin-low breast cancers." (PMID 29734696, 2018). "In a HER2-overexpressing breast cancer cell line, resistant to trastuzumab, the breast cancer-initiating CD44+/CD24-/low population was more sensitive to MTF treatment than the non-CD44+/CD24-/low population (estimated IC50 for MTF 1 ± 0.2 mM vs. 11 ± 2 mM)." (PMID 30241339, 2018). "In breast cancer tissues, AR and let-7a expression were correlated with the phenotype of CD44+/CD24-/low." (PMID 29423076, 2018). "Our current in vivo results are consistent with recent findings in MCF7 and MDA-MB-468 cells, two human breast cancer cell lines in culture, which showed significant reductions in the CD44(+)/CD24(-/low) CSC population, after treatment with doxycycline." (PMID 30364293, 2018). "The parental BT474 cells were almost exclusively CD24+/CD44-, which is characteristic of luminal breast cancer." (PMID 29879129, 2018). "The combined NRF1 overexpression and treatment with E2 also led to reprogramming of CD24+ and CD24−CD44− subpopulations with multiple breast cancer stem cell signatures containing ALDH1A1, EpCAM, CXCR4, or CD133." (PMID 30486409, 2018). "In subsequent studies, CD44+/CD24-/low and aldehyde dehydrogenase (ALDH) 1 were suggested as potential candidates for breast cancer stem cell markers." (PMID 29416796, 2018). "In conclusion, in ER-positive early breast cancer, the incidences of CD44+/CD24- and ALDH1-positivity by IHC, which are potential breast cancer stem cell markers, were very low." (PMID 29416796, 2018). "In breast cancer, EMT-type CSCs with high CD44 but low CD24 in the invasive front and MET-type CSCs expressing high level of ALDH1 in the tumor interior co-exist." (PMID 30038266, 2018). "In breast cancer tissue, we identified that AR expression was positively correlated with let-7a expression, but negatively with CD44+/CD24-/low phenotype of cancer cells." (PMID 29423076, 2018). "The DiD+ population displayed only partial overlap with the CD44+CD24−/low cell surface protein marker signature widely used to identify breast cancer stem cells, but was enriched for CD44+CD24+ cells." (PMID 30377878, 2018). "We further analyzed additional breast cancer cell lines, SCP28, MDA-MB-231 and BT20, for the expression of CD44v in CD24-/CD44+ population." (PMID 28300837, 2017). "Studies have shown that CD44/CD24 and ALDH1 expressed differently in different subtypes of breast cancers." (PMID 29062075, 2017).
breast cancer (continued). "We examined the association between CL tumors in our TMA cohort and known markers of breast cancer stem cells/tumor initiating cells including ALDH1 and CD44hi/CD24-/low." (PMID 28045912, 2017). "Several studies have shown that a sub-fraction of breast cancer cells termed BTICs undergo EMT reprogramming and typically exhibit a basal-like CD44+/CD24- phenotype harboring cancer stem-like features." (PMID 29207686, 2017). "To evaluate the CSC properties in MCF7 and doxo-resistant MCF7/ADR cells, we first evaluated the population of CD44+/CD24- and ALDH+ cells, which have been reported as the best markers for identification of breast cancer stem cells." (PMID 29050299, 2017). "In comparison to patient tumors, breast cancer cell lines differentially expressed ALDH, CD44 and/or CD24, making interpretation of experimental results difficult." (PMID 29348905, 2017). "Our results, together with other reports, suggest that high CD44/CD24 ratio and ALDH1+ are indicators for breast cancer malignancy." (PMID 29062075, 2017). "In breast cancer, the CD44+/CD24−/low cells from patients were found to be more tumorigenic than the CD44+/CD24+ cells when implanted into the mammary fat pads of the immunodeficient nonobese diabetic (NOD)/severe combined immunodeficient (SCID) mice." (PMID 29062075, 2017). "We investigated the expression of CD44, CD24 and ALDH1 in different subtypes of breast cancer cells, and explored their relationship with cancer progression." (PMID 29062075, 2017). "To study the relationship of CSCs and metastasis in breast cancer, we analyzed CSC contents of the isogenic MCF10 cancer cell lines by cell flow cytometry (FACS) with the prevailing markers CD24 and CD44." (PMID 28300837, 2017). "Here, we found that p62 expression was elevated in breast cancer stem cells (BCSCs), including CD44+CD24− fractions, mammospheres, ALDH1+ populations and side population cells." (PMID 27345399, 2017). "In this study, we investigated the expression of CD44, CD24 and ALDH1 in different subtypes of breast cancer, and explored the correlation between them and cancer progression both in vitro and in vivo." (PMID 29062075, 2017). "To this end, we tended to explore the dynamic changes of the CD44/CD24 ratio and the expression of ALDH1 during the development and metastasis of breast cancer." (PMID 29062075, 2017). "The expression of NMI was downregulated in breast cancer mammospheres compared with primary breast cancer and NMI was also downregulated in the CD44+CD24− cells compared with the CD44−CD24+ cell populations." (PMID 28492540, 2017). "Previous reports showed that increased expression of Twist and reduced expression of CD24 contribute to EMT and to CSC self-renewal through activation of transcription 3 (STAT3)-dependent pathways in liver and breast cancers." (PMID 28418843, 2017). "We first accessed the expression of CD24,CD44v and total CD44 in breast cancer clinical samples through immunofluorescence staining and observed both CD44v+ CSCs (CD24−/CD44+/CD44v+) and CD44v− CSCs (CD24-/CD44+/CD44v−) in tumor tissues." (PMID 28300837, 2017). "In contrast, luminal cancers express breast cancer differentiation markers (KRT20, CD24, ERBB2, and GATA3) and uroplakins which are markers of terminal urothelial differentiation." (PMID 28102366, 2017). "Cancer cells from TNBC often display a profile of cell surface markers that are similar to that of breast cancer stem cell (BCSC), characterized by the phenotype CD44+/CD24− in which CD44 is expressed at high levels but levels of CD24 are low or undetectable." (PMID 28760736, 2017). "The primary outcome will be the expression pattern of circulating CSC markers in breast carcinomas including EPCAM, CD44, CD24, ALDH1, CD133, and PIWIL2." (PMID 29258583, 2017). "H460 H-INV cells also express lower mRNA levels of CD24, which is proposed to be one of the molecular features when combined with CD44 expression (as CD44+/CD24low) for breast cancer stem cells." (PMID 27634890, 2016).
breast cancer (continued). "In breast cancer, CD44+/CD24- cells or ALDH1+ cells have both been reported to retain CSC characteristics." (PMID 27285982, 2016). "For example, CD24 was shown to increase phosphorylation of FAK and paxillin, and enhance integrin-dependent adhesion in breast cancer cells." (PMID 26830684, 2016). "We also found that high expression of the adhesion molecule CD24 correlated with poorer DFS in both TNBC and HR+ breast cancers." (PMID 28721382, 2016). "To isolate BCSCs, we used specific antibodies against surface markers (CD44, CD24 or Epithelial Cell Adhesion Molecule (ESA) in a luminal (MCF7) and a triple negative (MDA-MB-231) breast cancer cell line." (PMID 27876836, 2016). "An important feature of breast cancer stem cells is the expression of the surface markers CD44 and CD24." (PMID 27120585, 2016). "In contrast, in several transgenic mouse models of breast cancer, the consensus is that the CD24+/High sub-population rather than CD24Neg/Low sub-population enriches for TIC activities when CD24 is paired with either CD29 (ITGB1) or CD61 (ITGB3)." (PMID 27001172, 2016). "We also confirmed that miR-199a-5p significantly decreased the CD24-/CD44+ cell population (p = 0.0015), which is a well-reported subpopulation of breast cancer cells to have stem/progenitor cell properties." (PMID 27842518, 2016). "Comparison of the gene expression profiles of CD44+ and CD24+ cells revealed that CD44+ cells specifically expressed multiple stem cell markers, which expression correlate with poor survival outcomes in breast cancer patients." (PMID 27759034, 2016). "For example, CD24 was shown to support the expression of HER2 and contribute to decrease the sensitivity of HER2-positive breast cancer cells to lapatinib (HER2-targeted therapy)." (PMID 26830684, 2016). "The combination of CD44 and CD24, or aldehyde dehydrogenase 1 (ALDH1) alone, is a widely used cancer stem cell marker in breast cancer." (PMID 27768764, 2016). "Previous studies have found that tumor initiating cells in breast cancer exhibit a characteristic profile of the across cell surface markers CD44 and CD24." (PMID 27303921, 2016). "Futher research showed that breast cancer cells with EMMPRIN knocking-down exhibits a CD44−CD24+ phenotype and cells with human recombinant EMMPRIN exhibites a CD44+CD24− phenotype." (PMID 27325313, 2016). "We next assessed the level of BCSCs in the different breast cancer subtypes by examining the expression levels of the cancer stem cell surface markers CD44 and CD24." (PMID 27759034, 2016). "To investigate the differences caused by the loss of Llgl1 and the different populations that are observed, we evaluated the cells using breast cancer stem cell markers CD44, CD49f, and CD24." (PMID 27542214, 2016). "Using cell markers, such as CD44+/CD24-/low and ALDH positivity, is an additional method that differentiates between BCSCs and breast cancer cells." (PMID 27976692, 2016). "When mouse breast cancer cells were treated with pacilitaxel and epirubicin in serum-free condition and then maintained in suspension culture, they became mostly CD44+CD24- cells together with higher tumorigenic potential." (PMID 27766946, 2016). "Based on a number of basic studies, the combination of CD44 and CD24, or aldehyde dehydrogenase 1 (ALDH1) alone, is a widely used CSC marker in breast cancer." (PMID 27768764, 2016). "In the basal-likeMDA-MB-231 breast cancer cell model, the subpopulation of CD44 (+) CD24 (low+) cells exhibits stem cell properties in vitro and in vivo, metastatic gene signatures and greater invasion and metastatic potential." (PMID 26121683, 2015). "In human primary breast cancer xenografts, total and phosphorylated IGF1R expression is significantly higher in the CD44+CD24− sorted breast cancer stem cell population compared to the non-CD44+CD24− population." (PMID 25964777, 2015).
breast cancer (continued). "In breast cancer, EpCAM+ CD44+ CD24− lineage− cells are 10 times more likely to form tumors than the EpCAM− CD44+ CD24− lineage− population." (PMID 25636521, 2015). "Our results showed that DSF can inhibit the self-renewal capability of breast cancer cells, and reverse the expression of breast CSC markers, such as ALDH, CD44 and CD24." (PMID 26517513, 2015). "Breast cancer was one of the first solid malignancies in which CSCs were identified and characterized, mostly immunophenotypically as lin-/CD44+/CD24- cells." (PMID 25774169, 2015). "To further validate the idea GO was reducing stemness in MCF7-derived CSCs, we used a series of well-established breast cancer stem cell markers (CD44 and CD24), and quantitatively analyzed their expression by FACS analysis." (PMID 25708684, 2015). "Breast cancer cells that have low expression of CD24 in combination with high expression of CD44 (CD24−/CD44+) and high aldehyde dehydrogenase (ALDH) activity are known as breast cancer stem cells (BCSCs)." (PMID 26301220, 2015). "Breast cancer stem cells (CSCs), initially identified as CD44+/CD24- cells, are also known to express EMT markers." (PMID 26008969, 2015). "Several stemness markers have been described for the various histological subtypes of breast cancer, such as CD44, CD24, CD133, ALDH1, and ABCG2." (PMID 26504780, 2015). "As breast cancer progenitor cells have been previously identified as CD44+CD24−/low cells, the cellular expression of CD44 and CD24 was evaluated by flow cytometry." (PMID 25405855, 2015). "The anti-cancer effects of resveratrol were studied in CD24−/CD44+/epithelial specific antigen (ESA)+ populations of cancer stem cells selected from MCF-7 and MDA-MB-231 breast cancer cell lines." (PMID 26694341, 2015). "In our experiment, induction of EMT in breast cancer cells by exposure of TGF-β resulted in the acquisition of stem-like expression pattern (ALDH+, CD24− /CD44+) and self-renewal capacity." (PMID 26517513, 2015). "In line with CD24 expression using immunohistochemistry according to the subtypes of breast cancer, CD24 is highly expressed in luminal and HER2 subtypes of breast cancer cells, whereas low cell membrane expression was detected in MDA-MD–231 cells." (PMID 26444008, 2015). "Later, aldehyde dehydrogenase (ALDH) 1 expression and/or its activity were identified to be a marker for breast cancer stem/progenitor cells; fewer ALDH1 positive tumor cells than CD44+/CD24−/low tumor cells were required to generate tumors in vivo." (PMID 24558373, 2014). "CCAST identifies at least 5 distinct breast cancer cell states in SUM159 and sorted out these pure cell states automatically using only two surface markers, namely EPCAM and CD24." (PMID 25078380, 2014). "Claudin-low tumors express decreased levels of CDH1, are enriched for EMT markers, and are CD24 low/CD44 high, which are features of self-renewing breast cancer stem cells." (PMID 25252859, 2014). "Similar analysis of another PDX model (Luminal-like, HBCX-3), as well as MCF-7 and T47D cells confirmed CD24 and SSEA-4 expression in other ER+ breast cancer PDX models and cell lines." (PMID 25419568, 2014). "More interestingly, PDL192 response was found to be impacted by one EMT-related gene (vi) (VIM) and two cancer stem cell-related genes (vii and viii) (CD24 and CD133), both processes of high importance in breast cancer progression." (PMID 25375638, 2014). "Different lines of evidence indicate that breast cancer stem cells (BCSCs) display increased cell motility, invasion, and overexpress genes that promote metastasis and can be traced by CD44+/CD24−/low surface marker expression." (PMID 25401416, 2014). "On the SUM159 breast cancer cell line data, CCAST indicates at least five distinct cell states based on two surface markers (CD24 and EPCAM) and provides a gating sorting strategy that produces more homogeneous subpopulations than previously reported." (PMID 25078380, 2014).